LEPR (leptin receptor)
Diseases named in the same sentence as LEPR in open-access papers (continued):
Sharing a sentence is not in itself a finding about the gene and the disease.
cardiac hypertrophy (8 papers, 2012 to 2025). "The presence of cardiac hypertrophy in LepR-deficient and, to a lesser extent also in diet-induced obese mice, suggests that it develops as a result of the heart’s inability to respond to elevated systemic and/or cardiac leptin levels." (PMID 23841921, 2013). "On the other hand and as confirmed in our analysis, cardiac hypertrophy also develops in leptin- and LepR-deficient mice and may be reversed by leptin substitution." (PMID 23841921, 2013). "TGF- β1 is closely related to myocardial fibrosis, and leptin coincides with cardiac hypertrophy through binding of leptin to the short form leptin receptor in rat hearts." (PMID 38057836, 2023). "On the other hand, the presence of cardiac hypertrophy in obese mice with complete LepR signal disruption indicates that additional pathways also play a role." (PMID 23841921, 2013). "Additionally, a novel cardiac hypertrophy mouse model was constructed by inducible endothelium-specific deleting of leptin receptors (End.LepR-KO)." (PMID 32724454, 2020). "Taken together, our findings suggest that hearts from diet-induced obese mice continue to respond to chronically elevated leptin levels and that increased systemic and/or local leptin and enhanced cardiac LepR activation contribute the development of cardiac hypertrophy." (PMID 23841921, 2013). "Our findings suggest that hearts from obese mice continue to respond to elevated circulating or cardiac leptin, which may mediate cardioprotection via LepR-induced STAT3 activation, whereas signals distinct from LepR-Tyr1138 promote cardiac hypertrophy." (PMID 23841921, 2013).
gestational diabetes (8 papers, 2016 to 2021). Carbohydrate intolerance first diagnosed during pregnancy. "The db/+ mice, which carry one allele of leptin receptor mutation, have normal body weight and blood glucose, but higher fat mass and plasma leptin levels relative to wildtype mice, and develop gestational diabetes during pregnancy." (PMID 31619950, 2019). "Furthermore, women with the LEPR 223A/G or 223G/G genotypes had an increased risk of developing severe preeclampsia compared with women with the 223A/A genotype, whereas 2548 G/A LEP polymorphism was associated with gestational diabetes mellitus." (PMID 28051281, 2016). "Previous research has shown that genetic variability in maternal LEP and LEPR gene might be involved in pathological processes in pregnancy, including preeclampsia and gestational diabetes mellitus, while the role of the LEP and LEPR gene in the IRSA has not been investigated." (PMID 28051281, 2016).
Hypercholesterolemia (8 papers, 2010 to 2023). An increased concentration of cholesterol in the blood. "In a previous Korean population study, LEPR rs8179183 was associated with hypercholesterolemia, with the C allele of rs8179183 exhibiting a protective effect against abnormal HDL cholesterol levels." (PMID 32517169, 2020). "This study found that LEPR rs1137101 G carriers had two times higher risk of total cholesterol levels ≥200 mg/dl (OR = 2.1, 95 % CI 1.15–3.8; p = 0.008), AG/GG had a high risk of hypercholesterolemia (OR = 9.4, 95 % CI 2.1–41.5; p = 0.003)." (PMID 35387194, 2022). "Hypothalamic LEPR KOVMH mice fed a low fat diet also exhibited hypertriglyceridemia without concomitant hypercholesterolemia." (PMID 20624279, 2010).
Impaired glucose tolerance (8 papers, 2016 to 2025). An abnormal resistance to glucose, i.e., a reduction in the ability to maintain glucose levels in the blood stream within normal limits following oral or intravenous administration of glucose. "In pancreas-specific leptin receptor knockout mice, GSIS is impaired by high-fat feeding, and the ability to compensate for islet hypertrophy is reduced, resulting in impaired glucose tolerance." (PMID 35198097, 2022).
lymph node metastasis (8 papers, 2011 to 2024). "In the future, more studies should be conducted to explore the potential association of LEPR rs1137100 SNP with lymph node metastases." (PMID 38659416, 2024). "Analyses of LEPR rs1137100, rs1137101 and rs6588147 polymorphisms with lymph node metastases and stage." (PMID 38659416, 2024). "The study showed that leptin receptor expression was significantly associated with lymph node metastases and distant metastases." (PMID 36981858, 2023). "In contrast, another study showed that low LEPR expression increased the risk of lymph node metastasis by fourfold." (PMID 36941557, 2023). "Another correlation analysis also showed the positive association of leptin and leptin receptor with lymph node metastasis in endometrial cancer." (PMID 29682217, 2018). "We found that LEPR rs1137100 G>A SNP might increase the risk of lymph node metastases of NSCLC (OR = 1.35, 95% CI = 1.02–1.79, p = 0.038)." (PMID 38659416, 2024). "LEPR rs1137100 G>A SNP increases the risk of lymph node metastases." (PMID 38659416, 2024). "We analyzed the association of LEPR polymorphisms with lymph node metastases and stage." (PMID 38659416, 2024). "In addition, our findings indicated that LEPR rs1137100 G>A SNP might increase the risk of lymph node metastases (p = 0.038)." (PMID 38659416, 2024). "However, we found that LEPR rs1137100 G>A SNP might increase the risk of lymph node metastases (p = 0.038)." (PMID 38659416, 2024). "The LEP and LEPR expression were significantly correlated with lymph node metastasis and Ki-67 expression, respectively." (PMID 36941557, 2023). "Expression of leptin-receptor can be an independent poor prognostic indicator in the advanced gastric cancer group, Lauren diffuse group, and the lymph node metastasis group." (PMID 26147886, 2015). "Expression of leptin-receptor was correlated with adverse clinicopathological parameters, including lymph node metastasis and Lauren diffuse subtype." (PMID 26147886, 2015). "In renal cell carcinomas leptin and leptin receptor expression was well correlated with progression-free survival, venous invasion and lymph node metastasis." (PMID 21338489, 2011). "Additionally, leptin-receptor expression was compatible with poor survival outcome in 160 (47%) patients with lymph node metastasis, on univariate and multivariate analysis (P < 0.05)." (PMID 26147886, 2015). "Leptin-receptor positivity was related with poor survival of patients, especially in the AGC group, Lauren diffuse type group, and lymph node metastasis group, on univariate and multivariate analyses (P < 0.05)." (PMID 26147886, 2015). "Leptin-receptor expression was correlated with poor survival in 207 patients of the advanced gastric cancer (AGC) subgroup, 139 of the Lauren diffuse group, and in 160 patients with lymph node metastasis (P < 0.05, respectively)." (PMID 26147886, 2015). "Expression of leptin, pSTAT3, ERK, pAkt and HIF-1 alpha were correlated with the absence of lymph node metastasis, while leptin-receptor positivity was related with lymph node metastasis (P < 0.05, respectively)." (PMID 26147886, 2015). "The leptin-receptor may predict poor patient prognosis in the AGC, Lauren diffuse and lymph node metastasis subgroups, while EBV-positive status can show a good prognosis in the AGC." (PMID 26147886, 2015). "Present study found that LEPR expression did not significantly correlated with lymph node metastases (p = 0.66), but the expression rate of LEP in patients with lymph node metastasis was significantly higher than that of patients without lymph node metastasis (p = 0.002)." (PMID 36941557, 2023).
preeclampsia (8 papers, 2011 to 2025). Preeclampsia is a hypertensive disorder of pregnancy that is characterized by new-onset hypertension with proteinuria presenting after 20 weeks of gestation, and depending on mild or severe forms may initially present with severe headache, visual disturbances, and hyperreflexia. "This polymorphism is located in the intron region of the leptin receptor gene which is involved in the regulation of vascular function, angiogenesis, and inflammation, processes and is dysregulated in preeclampsia." (PMID 38910142, 2025). "In this study, we did not detect a significant difference in the genotypes or allele frequencies of the LEPR c.1968G>C variant in women with preeclampsia compared with controls." (PMID 32807109, 2020). "In light of these premises, our result suggests an independent association of LEPR c.668A>G variant with the development of preeclampsia in Sudanese women." (PMID 32807109, 2020). "The major finding in this study was the significant association between LEPR variant c.668A>G and preeclampsia." (PMID 32807109, 2020). "Two LEPR gene missense variants rs1137101 (c.668A>G) and rs1805094 (c.1968G>C) were investigated in Sudanese women with preeclampsia." (PMID 32807109, 2020). "A dearth of studies have investigated the association between LEPR variants rs1137101 and rs1805094 and preeclampsia worldwide." (PMID 32807109, 2020). "Although a significant association between LEPR c.668A>G and preeclampsia was reported only by Rigo et. al. in a study of Hungarian women, the G allele frequency that Rigo’s team reported was 0.425." (PMID 32807109, 2020). "This further confirmed the involvement of the G allele in the LEPR c.668A>G variant as an allele associated with the risk of developing preeclampsia." (PMID 32807109, 2020). "Women with the LEPR 223G allele (223A/G or 223G/G genotype) had almost a doubled risk of developing severe preeclampsia compared with women with the 223A/A genotype (adjusted OR 1.92)." (PMID 24991435, 2014). "Our research group reported various genetic (including leptin receptor gene polymorphisms) and soluble factors that were associated with the severity or complications of preeclampsia." (PMID 21906313, 2011). "Furthermore, Wang et. al., reported a significant association of LEPR c.C1968 homozygous + LEPR c.G1968 heterozygous with preeclampsia in a Chinese population." (PMID 32807109, 2020). "Leptin receptor gene (LEPR) variants may affect the leptin levels and act as a risk factor for preeclampsia." (PMID 32807109, 2020). "Elevated leptin concentrations (14.5 ng/mL) were associated with a 3.8-fold increased risk of preeclampsia (OR 3.8) whereas low soluble leptin receptor (SLR) (<28.5 ng/mL) was associated with a 6.3-fold increased risk of preeclampsia 6.3-fold (OR 6.3, 95%CI 1.7–23.2)." (PMID 24991435, 2014). "Thus, the LEPR gene is associated with increased risk of developing preeclampsia." (PMID 24991435, 2014). "Chromosome 1 contains many loci associated with preeclampsia, namely, MTHFR gene 1p36.3, FV gene 1q23 and LEPR gene 1p31.3." (PMID 32807109, 2020). "Leptin receptor immunoreactivity increased significantly in umbilical cord venous and arterial endothelial cells in normal pregnancy (n=12) compared with preeclampsia (n=7) endothelial cells." (PMID 29379664, 2017). "This study assessed the umbilical cord endothelial leptin receptor levels in preeclampsia and investigated the effect of leptin on endothelial interleukin-8 (IL-8) production." (PMID 29379664, 2017). "No investigation of an African population regarding the LEPR c.668A>G association with preeclampsia has been previously conducted." (PMID 32807109, 2020). "The corresponding preeclampsia versus control histologic scores (mean ± SEM) were 67.9±8.8 vs. 127.6±23.1, (p=0.011) for the leptin receptor and 55.4±8,0 vs. 93.7±17.1 (p=0.035), respectively, for the vein endothelial cells." (PMID 29379664, 2017).
preeclampsia (continued). "The distribution of LEPR c.1968G>C GC genotype was not significantly different between women with severe and mild preeclampsia [4/42 (9.52%) vs. 9/80 (11.25%); P = 0.987] or women with early and late preeclampsia [2/16 (12.5%) vs. 11/106 (10.37%); P = 0.858]." (PMID 32807109, 2020). "The distribution of the LEPR c.668A>G AG genotype was not significantly different between women with severe and mild preeclampsia [16/42 (38.09%) vs. 30/80 (37.5%); P = 0.984] or women with early and late preeclampsia [7/16 (43.75%) vs. 39/106 (36.79%); P = 0.796]." (PMID 32807109, 2020).
colitis (7 papers, 2013 to 2021). Inflammation of the colon. "Indeed, a recent study has demonstrated that leptin receptor deficient mice are resistant to experimentally induced Th2-mediated colitis." (PMID 23349631, 2013). "Strikingly, T-cells isolated from db/db mice delayed the development of colitis, indicating that the leptin/LepR axis is required for colitis progression by activating the T lymphocytes." (PMID 33935782, 2021). "In humans, increased expression of leptin receptor OBR in the mucosa of UC patients is associated with RHOA activation, while deficiency of OBR in mice protects against TNBS colitis in mice." (PMID 33406731, 2021). "To elucidate intrinsic leptin and LepR signaling in mucosal homeostasis, we exposed Leprdb/db and littermate control mice to DSS-induced colonic inflammation and examined them for sensitivity to colitis development." (PMID 33110098, 2020). "To confirm the previously established concept that leptin mediates pro-inflammatory effects, at least partly, via T cells, we performed a T cell transfer model of colitis and transferred naive CD4+ T cells lacking the signaling Ob-Rb-isoform of the leptin receptor." (PMID 30369924, 2018).
glioblastoma (7 papers, 2014 to 2023). The most malignant astrocytic tumor (WHO grade IV). "A study claimed that leptin receptor-positive glioblastoma cells were resistant to chemotherapy with temazolamide (TMZ) which failed to arrest cell proliferation and initiate apoptosis via STAT3 signaling." (PMID 30803210, 2019). "For this peptide with glioblastoma and BC cells and for leptin receptor (ObR) antagonists at high dose (10 μM) the pharmacological effects were reversed, and ADP355 inhibited CML cell growth to a smaller extent." (PMID 25368867, 2014). "Moreover, ectopic leptin receptor overexpression resulted in temozolomide (TMZ) resistance in glioblastoma, and the involvement of stem/progenitor cell properties and STAT3 signaling was indicated." (PMID 33799880, 2021). "Patients with glioblastoma showing poor prognosis have high leptin receptor levels." (PMID 33799880, 2021). "Patients of glioblastoma revealed poor prognosis as high leptin receptor levels were detected." (PMID 29682217, 2018). "In addition, the correlation of leptin receptor with vasculogenic mimicry (VM) formation had been reported in glioblastoma." (PMID 29682217, 2018). "Furthermore, overexpression of leptin receptor led to temozolomide (TMZ) resistance due to the stem/progenitor cell properties, and STAT3 signaling in glioblastoma." (PMID 29682217, 2018).
hypogonadotropic hypogonadism (7 papers, 2017 to 2025). Abnormal ovarian or testicular function due to insufficient hormonal stimulation from the hypothalamic-pituitary axis. "LEPR mutations have previously been reported to influence the risk of developing severe early-onset obesity, hypogonadotropic hypogonadism and hypothalamic hypothyroidism, which is similar to the clinical characteristics of leptin deficiency." (PMID 30442103, 2018). "Hypogonadotropic hypogonadism in LEPR-deficient individuals may be due to a defect both at the hypothalamic and the pituitary level." (PMID 30442103, 2018). "LEP and LEPR can be distinguished from MYT1L due to the association of hypogonadotrophic hypogonadism with LEP and LEPR SNVs." (PMID 28859103, 2017). "Likewise, re-expression of LepR on KP cells in LepR null mice also did not improve hypogonadotropic hypogonadism phenotype in these mice." (PMID 29643834, 2018).
myelofibrosis (7 papers, 2023 to 2024). A partial or complete replacement of the bone marrow stroma by fibrous tissue. "Specifically, in a mouse model of primary myelofibrosis with elevated levels of thrombopoietin (Tpo), MSCs that express the leptin receptor are responsible for forming myofibroblasts within the BM, which is a critical factor in the disease progression." (PMID 38314300, 2024). "Within the stromal compartment, the most striking change in myelofibrosis mice was an expansion of LEPR+ MSCs, with a more modest increase in fibroblasts and decrease in chondrocytes, OLCs and endothelial cells compared to controls." (PMID 39383242, 2024). "Recently, Leptin receptor–expressing MSCs were identified as the source of myofibroblasts in primary myelofibrosis." (PMID 36909480, 2023). "It was previously reported that LepR(+)CD140a(+)CD45(−) mesenchymal stromal cells are the primary cellular source of myelofibrosis in bone marrow." (PMID 37463149, 2023). "Specifically, in a mouse model of primary myelofibrosis with elevated levels of thrombopoietin (Tpo), MSCs that express the leptin receptor are responsible for forming myofibroblasts within the bone marrow, which is a critical factor in the disease progression." (PMID 38314300, 2024). "Since LepR+ MSCs were identified as the main source of myofibroblasts in primary myelofibrosis, further investigations are feasible to determine whether LepR+ mesenchymal/stromal stem cells are recruited and differentiate into myofibroblasts or fibroblasts in prostatic stromal hyperplasia." (PMID 38711089, 2024).
psoriasis (7 papers, 2012 to 2025). An autoimmune condition characterized by red, well-delineated plaques with silvery scales that are usually on the extensor surfaces and scalp. "Of the LEPR, multiple splice variants have been identified, but only the long isoform (Ob-Rb) can induce pathways that result in the activation of the nuclear factor kappa-B (NF-κB), which is the major transcription regulator of inflammatory mediators that are also active in psoriasis." (PMID 34685457, 2021). "LEPR rs1137101 was further analyzed in psoriasis sub-populations based on BMI values, such as normal weight, overweight, and obese." (PMID 34685457, 2021). "Regarding histological studies, leptin and leptin receptor expression were significantly higher in the skin of severe psoriasis patients with normal BMI than in patients with mild-moderate psoriasis and controls." (PMID 33260746, 2020). "However, reduced levels of leptin receptor mRNA and protein were detected in psoriasis lesions compared to healthy and uninvolved psoriasis skin." (PMID 38929716, 2024). "Regarding BGN, KLF2, and LEPR, the staining properties of epidermal cell nuclei, as well as dermal infiltrating cells and vascular endothelial cells tended to be decreased in both nonlesioned and lesioned areas of patients with AD versus normal and clinical controls (psoriasis)." (PMID 39938773, 2025). "CAV-1 and the leptin receptor are co-localized in keratinocytes, and CAV-1 silenced human keratinocytes produce more IL-6 by co-stimulation with leptin and IL-17, suggesting that obesity deteriorates psoriasis by enhancing cytokine production in CAV-1 deficient psoriasis keratinocytes." (PMID 36532050, 2022). "In addition, serum leptin levels, tissue leptin and leptin receptor expression showed a positive correlation with disease duration in patients with psoriasis The authors concluded that leptin might serve as a marker of severity and chronicity in psoriasis." (PMID 23144698, 2012).
schizophrenia (7 papers, 2020 to 2026). A major psychotic disorder characterized by abnormalities in the perception or expression of reality. "According to a systematic review, for FTO and leptin and leptin receptor genes (LEP and LEPR), for the methylenetetrahydrofolate reductase (MTHFR) gene, and for the serotonin receptor 2C gene (HTR2C), there is strong evidence of association with MetS in schizophrenia patients." (PMID 38540239, 2024).